MIR31 (microRNA 31)
Synonyms: hsa-mir-31; MIRN31; miR-31
Gene: MicroRNA gene on chromosome 9 (21,512,115 to 21,512,185, reverse strand). Ensembl gene ENSG00000199177.
Homologues: Orthologues: chimpanzee ptr-mir-31 (100% identical), macaque MIR31 (100% identical), mouse Mir31 (99% identical), guinea pig MIR31 (96% identical), pig ssc-mir-31 (96% identical), rabbit MIR31 (93% identical), tropical clawed frog xtr-mir-31a (83% identical), zebrafish dre-mir-31 (75% identical), rat Mir3554 (70% identical).
Diseases named in the same sentence as MIR31 in open-access papers:
MIR31 is named in the same sentence as 18 diseases in open-access papers, as found by Europe PMC text mining. Sharing a sentence is not in itself a finding about the gene and the disease. The quoted sentences say what the papers report.
colorectal cancer (2 papers, 2014 to 2022). A primary or metastatic malignant neoplasm that affects the colon or rectum. "As a novel therapeutic target, MIR31 has been extensively studied in various diseases such as colorectal cancer, nasopharyngeal carcinoma." (PMID 36590397, 2022).
gastric cancer (2 papers, 2016 to 2017). A primary or metastatic malignant neoplasm involving the stomach. "MIR31, which encodes p14ARF, are located at 9p21.3, a genomic region commonly deleted in many cancers, and E2F2overexpressionnormally leads via p14ARF, which may result in down-regulation of miR-31 in gastric cancer." (PMID 27174918, 2016). "MIR31 host gene (MIR31HG), also named lncRNA LOC554202, was found to be down-regulated in gastric cancer and bladder cancer, but up-regulated in breast cancer." (PMID 28415559, 2017).
colitis (1 paper, 2022). Inflammation of the colon. "Overall, our study uncovers the vital roles of MIR31 in balancing inflammation and the recovery of epithelia in colitis, providing potential clues for the development of therapeutic targets in drug design." (PMID 36590397, 2022). "We next apply our model to quantitatively dissect the functional roles of MIR31 in colitis." (PMID 36590397, 2022). "Meanwhile, MIR31 expression increases gradually to prevent DSS-induced colitis." (PMID 36590397, 2022). "While the functional role of MIR31 in colitis and related diseases remain elusive." (PMID 36590397, 2022). "MIR31 can promote epithelial regeneration during skin wound healing by mediating inflammatory signaling, and target IL-25 to regulate IL-12/23-mediated Th1/Th17 inflammatory responses during colitis." (PMID 36590397, 2022). "There are four major MIR31 target proteins, Gp130, IL17RA, Axin1, and Lats1/2, with certain probabilities of acting on inflammation and regeneration in colitis." (PMID 36590397, 2022). "Experimental observations suggest that the expression of MIR31, phosphorylated p65 (p-65), and phosphorylated STAT3 (p-STAT3) present an “adaptation” behavior in dextran sulfate sodium (DSS)-induced mouse colitis, which are well reproduced by our model." (PMID 36590397, 2022). "MIR31 promotes epithelial regeneration in low levels of DSS-induced colitis but inhibits inflammation with high DSS levels, which is dominated by the competition for MIR31 to either inhibit inflammation or promote epithelial regeneration by binding to different targets." (PMID 36590397, 2022). "Hence, above observations determine that MIR31 regulates inflammatory response through suppressing p65 and STAT3 activation, but promoting the recovery of epithelia during colitis." (PMID 36590397, 2022).
endometrial cancer (1 paper, 2014). Primary or metastatic malignant neoplasm involving the endometrium (mucous membrane that lines the endometrial cavity). "MIR31 is a potential new molecular marker for predicting the risk of recurrence and prognosis of endometrial cancer." (PMID 24779718, 2014). "We aimed to investigate whether MIR31 is an oncogene in human endometrial cancer and identify the target molecules associated with the malignant phenotype." (PMID 24779718, 2014). "In order to identify the target molecule of MIR31, a luciferase reporter assay was performed, and the corresponding downstream signaling pathway was examined using immunohistochemistry of human endometrial cancer tissues." (PMID 24779718, 2014). "MIR31 functions as an oncogene in endometrial cancer by repressing the Hippo pathway." (PMID 24779718, 2014).
hepatocellular carcinoma (1 paper, 2022). A malignant tumor that arises from hepatocytes. "PEX5, a novel target of MIR31, is also proven to be a therapeutic option in hepatocellular carcinoma." (PMID 36590397, 2022).
keloid (1 paper, 2023). An irregularly shaped, elevated mark on the skin caused by deposits of excessive amounts of collagen during wound healing. "In addition, our study also showed that MIR31 was related to multiple biological processes that were linked to wound healing, including fibrosis and keloid." (PMID 37588448, 2023).
osteonecrosis (1 paper, 2022). A none disease characterized by death of bone tissue due to a lack of blood supply. "MIR31 host gene (MIR31HG) polymorphisms play important roles in the occurrence of osteonecrosis." (PMID 36057712, 2022).
prostate carcinoma (1 paper, 2022). A carcinoma that arises from epithelial cells of the prostate gland. "The down-regulation of MIR31 disrupts cellular homeostasis and promotes the evolution and progression of prostate cancer." (PMID 36590397, 2022).
cancer (3 papers, 2014 to 2022). A tumor composed of atypical neoplastic, often pleomorphic cells that invade other tissues. "The MIR31 host gene (MIR31HG) is a newly identified long non-coding (lnc)RNA that exhibits ambiguous roles in cancer." (PMID 35743003, 2022). "Furthermore, MIR31 has been reported to be an oncomir in various human cancers, including colorectal, esophageal, lung, oral and head and neck cancer, and a tumor suppressor gene in breast and gastric cancers and malignant mesothelioma." (PMID 24779718, 2014). "MIR31 is an oncomir in several human cancers and a tumor suppressor gene in others." (PMID 24779718, 2014).
tumor (3 papers, 2014 to 2026). "It is plausible that MIR31 represses the expression of tumor suppressor genes, such as LATS2, to act as an oncomir and indirectly promotes the transcription of genes related to cell cycle control and tumorigenesis." (PMID 24779718, 2014). "A significant increase in tumor weight was observed in the HEC-50B cells with MIR31 overexpression compared with that noted in the controls in the nude mice subcutaneous tumor model." (PMID 24779718, 2014). "The overexpression of MIR31 significantly promoted anchorage-independent growth in vitro and significantly increased the tumor forming potential in vivo." (PMID 24779718, 2014). "In addition, MIR31 is proven to be a target for inhibiting tumor growth and metastasis." (PMID 36590397, 2022). "We speculate that MIR31 has a specific function in each type of malignancy, and several mechanisms, including methylation-dependent silencing and local deletion, may explain its different roles in different tumor types." (PMID 24779718, 2014). "MIR31 deletion upregulated LYN, enhancing stiffness perception and promoting O-GlcNAc addition to NICD1, finally resulting in mechanoadaptation- and tumor stemness-driven recurrence." (PMID 41632535, 2026).
MIR31 also shares sentences with these, for which no sentence is quoted: adenocarcinoma (1 paper); bladder cancer (1); breast carcinoma (1); Duchenne muscular dystrophy (1); head and neck carcinoma (1); lung carcinoma (1); nasopharyngeal carcinoma (1); viral infection (1).